ASPM (assembly factor for spindle microtubules)
Diseases named in the same sentence as ASPM in open-access papers (continued):
Sharing a sentence is not in itself a finding about the gene and the disease.
microcephaly (continued). "Thirdly, in 45 families with a less restricted phenotype including microcephaly and mental retardation, but regardless of other neurological features, only 3 (7%) had an ASPM mutation." (PMID 19028728, 2009). "However, several other proteins such as Ndel1, the partner of LIS1 involved in lissencephaly, ASPM involved in microcephaly, or spastin involved in hereditary spastic paraplegia, are also neuronal MAPs." (PMID 18782428, 2008). "Interestingly, two truncated forms of ASPM (missing exons 1–7 or 1717 C-terminal amino acids) in mice caused microcephaly, while only the mice lacking the C-terminal domain showed spindle misorientation." (PMID 37599996, 2023). "Similarly, to NSD1, ASPM (abnormal spindle-like, microcephaly-associated; MCPH5) undergoes positive selection in selected exons throughout the primate lineage leading to humans and currently is associated to microcephaly." (PMID 36550402, 2022). "Finally, in an investigation of the ASPM-dependent pathogenesis of microcephaly, we report that the cortical organoids generated from primary microcephaly patient-derived iPSCs were unable to form normal cortical lamination resulting in defective neuronal activity." (PMID 29058117, 2017). "Infratentorial anomalies such as cerebellar hypoplasia, with or without an enlarged posterior fossa, have been described, especially in ASPM-, CDK5RAP2-, and WDR62-related microcephaly." (PMID 35456440, 2022). "In addition to recapitulating the human microcephaly better than the mouse modes, Aspm KO ferrets show a displacement of aRG to the oSVZ where they resemble bRG, suggesting an evolutionary mechanism by which ASPM regulates cortical expansion by controlling the ratio between aRG and bRG." (PMID 35069108, 2021). "Decreased levels of RNA of a variety of genes involved in cell cycle progression and microcephaly including Microcephalin, CDK5RAP2, CASC5, ASPM, CENPJ, STIL, CEP135, and CDK6 was also observed." (PMID 29276699, 2017). "Among these are KNL1, ASPM, and CITK, which are especially required during neurogenesis being extensively expressed in the VZ and SVZ, are known to induce the accumulation of DNA lesions and microcephaly when defective." (PMID 37881689, 2023). "Strikingly, most mouse models of microcephaly where the candidate genes (CDK5RAP2, CPAP, ASPM, Wdr62, and Plk4) were either completely ablated or highly overexpressed have invariably displayed apoptosis as a prominent mechanism for causing NPCs depletion and microcephaly." (PMID 32457578, 2020). "Furthermore it also indicates that beside ASPM, WDR62 gene is a relevant contributor for autosomal recessive primary microcephaly in Pakistan, being responsible for about 4% cases." (PMID 21961505, 2011). "The identification of UBE3A as an ASPM interactor is not unexpected as more than 80% of AS patients have microcephaly." (PMID 21633703, 2011). "The identification of UBE3A as an ASPM interactor is not surprising as more than 80% of Angelman syndrome patients have microcephaly." (PMID 21633703, 2011). "Although the precise mechanism that underlies microcephaly caused by pathogenic ASMP mutations still has not been fully elucidated, both mechanisms result in a marked reduction of ASPM protein in neuronal cells, which results in reduced fetal brain growth and microcephaly." (PMID 33643967, 2020). "This is not surprising as several of the key primary microcephaly genes (CDK5RAP2, ASPM, WDR62, and MCPH1) are essential for the control of mitosis and cell cycle progression." (PMID 36845425, 2023). "ASPM (abnormal spindle-like microcephaly), also known as MCPH5, is mainly distributed between centrosomes and spindle microtubules, and the absence of ASPM results in the disruption of spindle assembly and mitotic processes." (PMID 37184686, 2023).
Primary microcephaly (26 papers, 2007 to 2025). Head circumference below 2 standard deviations below the mean for age and gender at birth. "In the present study, we observed a high frequency of ASPM variants in the genetic analysis of 30 consanguineous families exhibiting features of NDDs, particularly those associated with autosomal recessive primary microcephaly." (PMID 39281811, 2024). "ASPM is a mitotic spindle protein; mutations in the ASPM gene are the most common cause for primary microcephaly." (PMID 34539790, 2021). "Abnormal spindle-like microcephaly-associated (ASPM) gene encodes a spindle protein that is commonly implicated in primary microcephaly." (PMID 34142045, 2021). "Genes associated with primary microcephaly were often differentially expressed during development, with highest expression during the early embryonic and fetal periods (ASPM, WDR62, MCPH1, STIL, KIF23 and TTI1)." (PMID 32182809, 2020). "Collectively, three novel variants were identified in the ASPM gene from three different primary microcephaly families." (PMID 33643967, 2020). "In this study, we identified three novel mutations in three different primary microcephaly families related to the ASPM gene from Saudi population." (PMID 33643967, 2020). "The ASPM gene is related to primary microcephaly type 5, which is the most common cause of autosomal recessive inherited primary microcephaly." (PMID 26846091, 2016). "For example, the mutation in abnormal spindle-like microcephaly-associated protein (ASPM) are the most common cause of primary microcephaly characterized by a small brain and mental retardation in humans." (PMID 24260314, 2013). "Homozygous mutations in ASPM are a cause of primary microcephaly and the gene shows evidence of positive selection in both the human lineage and the ancestral lineage of the apes." (PMID 20573239, 2010). "ASPM mutations are the most common cause of primary microcephaly in humans." (PMID 37184686, 2023). "In this study, we reported three novel mutations in the ASPM gene causing primary microcephaly." (PMID 33643967, 2020). "A substantial number of 12 of these genes were deregulated, most significantly ASPM, a well-characterized MCPH gene, and CDK5RAP2, mutations in which have been reported in patients with primary microcephaly and/or Seckel syndrome." (PMID 35099000, 2022). "Well-known genetic causes of primary microcephaly are mainly genes involved in the assembly of centrosomes and cilium, such as CDK5RAP2, ASPM, CPAP, and WDR62." (PMID 34539790, 2021). "LWAS postulates many other genes associated with primary microcephaly, such as MCPH1 (rank 4), MCPH2 (rank 7), ASPM (rank 15), and must therefore also be considered as candidates causing or impacting the development of Seckel syndrome." (PMID 26919047, 2016). "This study confirms that mutations in ASPM are the most common cause of MCPH, that ASPM mutations are restricted to individuals with an MCPH phenotype, and that ASPM testing in primary microcephaly is clinically useful." (PMID 19028728, 2009). "By and large, primary microcephaly patients are phenotypically indistinguishable, however, recent studies in patients with mutations in MCPH1, WDR62 and ASPM genes showed a broader clinical and/or cellular phenotype." (PMID 21668957, 2011).
autosomal recessive primary microcephaly (24 papers, 2009 to 2023). "Mutations in the human ASPM gene can lead to the defective proliferation of neural progenitor cells, resulting in autosomal recessive primary microcephaly (MCPH)." (PMID 37051591, 2023). "In this study, we report on a child, born to consanguineous parents, with dual molecular diagnoses: autosomal recessive primary microcephaly-5 (MCPH5) and nephropathic cystinosis, due to homozygous pathogenic variants in the ASPM and CTNS genes, respectively." (PMID 36553645, 2022). "Mutations of the ASPM gene are known to cause autosomal recessive primary microcephaly, where some patients also have hereditary hearing loss." (PMID 35741759, 2022). "In contrast to those disorders with dominant inheritance pattern, bi-allelic mutations in ASPM cause autosomal recessive primary microcephaly 5, a rare syndrome belonging to the MCPH group." (PMID 34946966, 2021). "Mutations in the TTI2 gene have been associated with autosomal recessive ID and the ASPM gene has been implicated in autosomal recessive primary microcephaly-5." (PMID 29794985, 2018). "In this context, causative genes of human autosomal recessive primary microcephaly, such as ASPM and MCPH1, are attractive candidates, as many of them show positive selection during primate evolution." (PMID 25870538, 2015). "In mammals, ASPM is involved in the regulation of neurogenesis, and mutations in ASPM have been linked to primary autosomal recessive microcephaly (MCPH)." (PMID 23152892, 2012). "Mutations in the Abnormal Spindle Microcephaly related gene (ASPM) are the commonest cause of autosomal recessive primary microcephaly (MCPH) a disorder characterised by a small brain and associated mental retardation." (PMID 21044324, 2010). "Defect in ASPM was reported to be associated with autosomal-related recessive primary microcephaly." (PMID 36237324, 2022). "Furthermore, knockdown of abnormal spindle microcephaly (ASPM), a causative gene for autosomal recessive primary microcephaly (MCPH, for microcephaly primary hereditary), disturbs neuronal migration as well as neural progenitor proliferation in mice." (PMID 23294285, 2013). "Deleterious variants in the ASPM gene are the cause of autosomal recessive primary microcephaly (MCPH), which is a neurodevelopmental disorder that exhibits genetic heterogeneity, being associated with variants in at least 20 recessive loci." (PMID 36553645, 2022). "Truncating mutations of the abnormal spindle-like microcephaly associated (ASPM) gene cause autosomal recessive primary microcephaly (MCPH) in humans." (PMID 32066665, 2020). "Mutations in a number of identified genes have been found to underlie autosomal recessive primary microcephaly (MCPH) (e.g., MCPH1, ASPM, CASC5, and WDR62) and thanatophoric dysplasia (FGFR3), a subtype of megalencephaly." (PMID 31338027, 2019). "Autosomal primary recessive microcephaly (MCPH) is a disorder in neurogenesis caused by at least nine genes, six of which encode centrosome components (CEP63, CEP135, CEP152, CDK5RAP2/Cnn, CPAP /MCPH6, and STIL/MCPH7) and two encode proteins associated with spindle poles (ASPM and WDR62)." (PMID 30687396, 2018). "So far, five genes associated with autosomal recessive primary microcephaly (MCPH) have been identified in patients: MCPH1, CDK5RAP2, ASPM, CENPJ, and STIL/SIL." (PMID 28933765, 2017). "Autosomal Recessive Primary Microcephaly (MCPH) is one of those, for which seven loci (MCPH1-MCPH7) with the corresponding genes (MCPH1, WDR62, CDK5RAP2, CEP152, ASPM, CENPJ, and STIL) have been reported so far." (PMID 24148351, 2013).
glioma (24 papers, 2010 to 2025). A benign or malignant brain and spinal cord tumor that arises from glial cells (astrocytes, oligodendrocytes, ependymal cells). "Studies have shown that ASPM expression is associated with the WHO grade of gliomas, with higher expression in GBM and recurrent tumors." (PMID 39458936, 2024). "On the other hand, aberrant ASPM expression is tightly associated with malignant progression of gliomas, and in vitro short interference of ASPM resulted in G1-phase cell cycle arrest of tumor cells." (PMID 21559369, 2011). "This study indicates that ASPM is tightly associated with the malignant progression of gliomas and that its knockdown produces extensive death of glioma cells in vitro." (PMID 20142996, 2010). "Collectively, these data demonstrated that ASPM may lead to cell cycle arrest of glioma cells by causing abnormal expression of late‐G0/G1–related proteins." (PMID 32667745, 2020). "Up-regulation of the ASPM gene has recently been shown and recognized as a poor outcome factor in glioma and liver malignancies." (PMID 36849756, 2023). "The downregulation of ASPM can affect DNA double-strand repair by the DNA-PK pathway and enhance the sensitivity of radiotherapy in glioma cells, while high expression of ASPM is negatively related to TMZ sensitivity in LGG." (PMID 35846118, 2022). "Through gene correlation analysis, we identified genes positively correlated with CKAP2L, including BUB1, TTK, and ASPM, which can promote the development of glioma and treatment resistance." (PMID 34631884, 2021). "Aberrantly expressed ASPM regulated by transcriptional factor FoxM1 triggers the malignant progression of gliomas." (PMID 34987580, 2021). "FoxM1 overexpression significantly increased the expression of ASPM and promoted the proliferation and migration of glioma cells, which was abolished by ASPM ablation." (PMID 32667745, 2020). "In summary, the present study is the first to reveal that ASPM promoted glioma cell proliferation, migration and invasion and tumour growth, which is mediated by the transcriptional activation of FoxM1." (PMID 32667745, 2020). "Patients with high expression of ASPM in glioma had a significantly poor prognosis (n=262, p < 0.0001)." (PMID 31905171, 2020). "In the present study, we found that knockdown of ASPM significantly reduced the migration ability of glioma cells." (PMID 32667745, 2020). "Collectively, these results indicated that down‐regulation of ASPM can inhibit the migration and invasion ability of glioma cells." (PMID 32667745, 2020). "We found that BRCA1, CHD1 and FoxM1 mRNA expression was significantly positively correlated with ASPM mRNA expression in glioma tissues, and the highest correlation coefficient was found between FoxM1 and ASPM expression." (PMID 32667745, 2020). "More importantly, further validation in the CGGA and TCGA‐LGG data sets and clinical samples also demonstrated that the expression of ASPM mRNA was increased with the increase in glioma grades, and the high expression of ASPM indicated a worse prognosis." (PMID 32667745, 2020). "Our results demonstrated for the first time that FoxM1 can directly activate the expression of ASPM by binding to the promoter, thereby regulating the proliferation, migration and invasion of glioma cells." (PMID 32667745, 2020). "At present, the mechanism that regulates the abnormal expression of ASPM in gliomas remains unrevealed." (PMID 32667745, 2020). "We then examined the expression of ASPM in glioma cell lines and discovered that the mRNA and protein expression levels of ASPM were similarly upregulated in 4 human glioma cell lines compared with the normal glial cell line." (PMID 31905171, 2020). "org), we discovered that ASPM was moderately expressed in glioma tissues but weakly expressed in normal cerebral cortex specimens." (PMID 31905171, 2020). "In the current work, we found that knockdown of ASPM can induce cell arrest at G0/G1 phase and down‐regulate CyclinE expression in glioma cells." (PMID 32667745, 2020).
glioma (continued). "Collectively, our results demonstrated for the first time that aberrant ASPM expression mediated by transcriptional regulation of FoxM1 promotes the malignant properties of glioma cells." (PMID 32667745, 2020). "We observed that ASPM mRNA was increased obviously in glioma tissue, and higher ASPM mRNA expression predicted worse disease prognosis." (PMID 32667745, 2020). "In this study, we demonstrated for the first time that FoxM1 can directly regulate ASPM transcription in glioma cells, thereby affecting their expression and thereby regulating the proliferation, migration and invasion of glioma cells." (PMID 32667745, 2020). "In gliomas, ASPM is elevated in glioma tissues, and ASPM knockdown significantly represses the proliferation of glioma spheres." (PMID 32667745, 2020). "In gliomas, the expression of ASPM increased with the glioma grade, and ASPM expression is significantly higher in recurrent glioma than that in primary gliomas." (PMID 32667745, 2020). "ASPM was highly expressed in glioma cell lines U87‐MG and U251, and knockdown of ASPM expression in these cells significantly repressed the proliferation, migration and invasion ability and induced G0/G1 phase arrest." (PMID 32667745, 2020). "In order to investigate the role of ASPM in glioma, we primarily detected the expression levels of ASPM mRNA in different glioma cell lines." (PMID 32667745, 2020). "Increasing evidence demonstrates that ASPM was upregulated in a variety of tumors, including ovarian cancer, prostate cancer, glioma, and hepatocellular carcinoma." (PMID 31106147, 2019). "A higher expression of ASPM was also seen in 4/7 recurrent gliomas compared to their corresponding primary gliomas." (PMID 23472065, 2013). "To better characterize the involvement of ASPM in gliomas, we investigated the mRNA expression in 175 samples, including 8 WHO Grade II, 75 WHO Grade III and 92 WHO Grade IV tumors." (PMID 20142996, 2010). "Preliminary results with western blot analysis showed that ASPM was also expressed at the protein level in gliomas and overexpressed in Grade IV gliomas as compared to Grades III and II." (PMID 20142996, 2010). "Experimental evidence supports this finding since we found a progressive increase in ASPM mRNA expression in serial passages of gliomaspheres in vitro and in mouse glioma xenografts in vivo." (PMID 20142996, 2010). "Although we found that ASPM was also expressed at the protein level in all glioma grades and overexpressed in Grade IV gliomas, it is worth noting that the results were less striking." (PMID 20142996, 2010). "ASPM expression level increased between NT tissue and Grade II gliomas (p < 0.05), between Grade II and Grade III (p < 0.005), and between Grade III and Grade IV (p = 0.0001)." (PMID 20142996, 2010). "The spindle molecule ASPM has been shown to be involved in the malignant progression of gliomas possibly through expansion of a cancer stem cell compartment." (PMID 20885975, 2010). "We measured ASPM expression via qRT-PCR in 175 gliomas (8 Grade II, 75 Grade III and 92 Grade IV) and in three non-neoplastic brain tissues (NT)." (PMID 20142996, 2010). "ASPM is involved in the cell cycle and microtubule stability in gliomas, suggesting that ASPM depletion may mimic microtubule destabilizers; however, specific ASPM inhibitors have not been discovered yet." (PMID 39458936, 2024). "A previous study has shown that ASPM was highly expressed in glioma cells, and the abnormal expression of ASPM regulated by transcriptional regulation of FoxM1 contributed to the aggressiveness of gliomas." (PMID 37229243, 2023). "However, recent studies revealed that transcription factor FoxM1 bound to the promoter of ASPM and activated the transcription of ASPM directly in glioma cells and gastric cancer cells." (PMID 34428354, 2021). "Shortly after, ASPM was associated with glioma grade, showing increased expression from non-tumoral samples to grade II, III, and IV gliomas." (PMID 33801334, 2021).